MLKL (mixed lineage kinase domain like pseudokinase)
Diseases named in the same sentence as MLKL in open-access papers (continued):
Sharing a sentence is not in itself a finding about the gene and the disease.
pancreatic cancer (20 papers, 2016 to 2025). "LA and αLA increased lipid peroxidation and phosphorylation of RIP3 and MLKL in pancreatic cancers, which were negated by ferroptosis inhibitor, ferrostatin-1, restoring back to BSA control levels." (PMID 38388563, 2024). "Despite IMB5036′s ability to partially activate apoptosis and pyroptosis, its primary mode of action is necroptosis, initiated by the upregulation of RIPK1, RIPK3, and largely MLKL in pancreatic cancer cells." (PMID 37893166, 2023). "The aurora kinase inhibitor, CCT137690, triggered the necroptosis of pancreatic cancer cells by RIPK1, RIPK3, and MLKL, and hindered the growth of in situ pancreatic tumors in mice." (PMID 36981005, 2023). "In line with this, increased levels of MLKL were detected in the invasive form of human pancreatic cancer tissue." (PMID 37373257, 2023). "The expression of RIP3 and MLKL is upregulated in pancreatic cancer tissues, and further findings indicate that necroptosis factors can promote pancreatic cancer cell migration and invasion through the CXCL5–CXCR2 axis." (PMID 36553511, 2022). "RIPK3 and MLKL were also found increased in human pancreatic cancer tissues compared with normal pancreas, which promote pancreatic cancer cell migration and invasion." (PMID 39872161, 2022). "Other reports also describe higher RIPK3 and MLKL levels in human pancreatic cancer tissue, with MLKL expression even more intense at the tumor invasion front." (PMID 35422482, 2022). "Another outstanding example is the MLKL gene, which was shown to be up-regulated in pancreatic cancer, as we observed with Reboot, especially in tumor-invasion conditions." (PMID 34316711, 2021). "We used immunohistochemistry and western blot analysis to evaluate expression of the key mediators of necroptosis—receptor-interacting serine/threonine protein kinase 3 (RIP3) and mixed lineage kinase domain-like (MLKL)—in human pancreatic cancer." (PMID 31999765, 2020). "RIP3 and MLKL are highly expressed in human pancreatic cancer tissues compared with normal pancreas." (PMID 31999765, 2020). "The researchers found that the combination of BV6 and 2′3′-cGAMP effectively triggered necroptosis in pancreatic cancer through MLKL phosphorylation and the stimulation of NF-κB, type I interferons (IFNs), TNFα, and IFN-regulatory factor 1 (IRF1) signaling pathways." (PMID 37893166, 2023). "In pancreatic cancer, CHMP4C facilitates progression by inhibiting necroptosis via the RIPK1/RIPK3/MLKL pathway, thereby emphasizing its role in cell survival and proliferation." (PMID 40893939, 2025). "In pancreatic cancer, its overexpression accelerates tumor progression by inhibiting necroptosis through the RIPK1/RIPK3/MLKL signaling cascade." (PMID 41180485, 2025). "They utilized genetically engineered mouse models and human pancreatic cancer cell lines to study the role of specific necrosome components, including RIP3 and MLKL, in pancreatic tumor growth and immune evasion." (PMID 40064873, 2025). "For instance, studies on patients with pancreatic cancer found that in addition to RIPK1/3, MLKL protein expression was also elevated." (PMID 37373257, 2023).
lung cancer (17 papers, 2020 to 2025). A malignant neoplasm involving the lung. "Decreased expression of RIPK3 or MLKL was found to be associated with worse disease free survival of lung cancer." (PMID 35871768, 2022). "Conversely, SKP2‐mediated degradation of MLKL contributes to cisplatin resistance in non‐small cell lung cancer (NSCLC) cells." (PMID 39619229, 2024). "The compound tanshinol A has been shown to elevate intracellular ROS and MLKL levels in lung cancer." (PMID 39619229, 2024). "ROS generation contributes to the activation of MLKL during necroptosis in lung cancer cells and serves as a downstream event triggered by MLKL upon the induction of necroptosis in colon adenocarcinoma cells." (PMID 39090114, 2024). "Increased phosphorylation of RIPK1/RIPK3 and MLKL activity indicates that acetylshikonin promoted necroptosis in lung cancer cells." (PMID 38126996, 2023). "The results indicated that the genes FADD, TNFRSF1A, CASP9, MLKL, and CASP4 were the risk factor for lung cancer patients (p < 0.05)." (PMID 36874021, 2023). "MLKL can also trigger necroptosis independently of Ripk3 in tanshinol A-induced lung cancer cell death, anti-CD147 antibody-induced hepatocellular carcinoma cell death, radiation-induced antitumor immunity, and autoimmune hepatitis." (PMID 36828808, 2023). "Taken together, these results suggest that acetylshikonin activates the necroptosis pathway via the RIPK1/RIPK3/MLKL axis in lung cancer cells." (PMID 38126996, 2023). "For example, VACV infection in lung cancer cells showed decreased caspase-8 activity with a marked increase in phosphorylated mixed lineage kinase domain-like (MLKL), a known obligate effector of necroptosis." (PMID 36755812, 2022). "For example, Ad infection was reported to mediate necroptosis via upregulating RIP3 and promoting the phosphorylation of mixed-lineage kinase domain-like (MLKL) in lung cancer cells." (PMID 34685652, 2021). "Furthermore, tanshinol A (TSA) inhibits the growth of lung cancer cells by triggering necroptosis via MLKL." (PMID 37976123, 2023). "In the current study, we sought to determine whether the mechanism by which acetylshikonin induces lung cancer cell death is related to necroptosis by observing the phosphorylation of MLKL via immunofluorescence staining at various time intervals after treating cells with 2.5 μM acetylshikonin." (PMID 38126996, 2023). "Interestingly, tanshinol A induces necroptosis via MLKL but not through RIPK1 or RIPK3 in lung cancer; it causes the massive production of ROS, increases the phosphorylation level of MLKL and promotes MLKL transfer to the plasma membrane to execute necroptosis." (PMID 39584140, 2024). "On the other hand, it was reported that necroptosis could be mediated by MLKL but independent of RIPK1/RIPK3 signaling in transhinol A-stimulated lung cancer cells." (PMID 36030201, 2022). "On the other hand, there is also evidence that necroptosis may promote carcinogenesis by inducing adaptive immunosuppression; for instance, RIPK1 is overexpressed in glioblastoma, lung cancer, and pancreatic ductal adenocarcinoma (PDAC), and RIPK3 and MLKL are highly expressed in PDAC." (PMID 35769473, 2022).
steatosis (17 papers, 2017 to 2025). Increased lipid within the cytoplasm of cells. "Analysis of liver pathology also revealed that MLKL-deficient mice were markedly protected from steatosis and ballooning from HFD feeding, with a similar trend in aging ND-fed mice." (PMID 39532538, 2025). "Increased MLKL expression in macrophages was found in ethanol-exposed livers, and myeloid MLKL deficiency exacerbated ethanol-induced steatosis and hepatocyte injury by impairing macrophage phagocytic capability." (PMID 36765043, 2023). "When used as either a prophylactic or curative treatment for HFD-fed mice, RIPA-56 caused a downregulation of MLKL and a reduction of liver injury, inflammation and fibrosis, as well as of steatosis." (PMID 33803539, 2021). "MLKL expression in liver tissue of NAFLD patients increases in correlation with the severity of associated pathological changes, such as steatosis, ballooning, and inflammation." (PMID 39244571, 2024). "Nevertheless, studies investigating the consequences of inhibiting necroptosis through targeting either RIPK3 or MLKL in mice have presented contradictory outcomes concerning inflammation, steatosis, and fibrosis, with the observed effects varying based on the dietary conditions." (PMID 38474061, 2024). "In addition, in patients with NASH, serum concentrations of RIPK1 and MLKL increase with activity, and RIPK1 inhibition improves NASH features in high-fat diet-fed mice and reverses steatosis via an MLKL-dependent mechanism." (PMID 36110858, 2022). "Furthermore, it reversed steatosis via an MLKL-dependent mechanism, which was at least partially involved in mitochondrial respiration." (PMID 33374660, 2020). "Compared to control mice, MLKL-KO mice fed with the HFD exhibited reduced NAS, steatosis score, inflammation, and ballooning degeneration." (PMID 39244571, 2024). "In our study, we confirm the existence of necroptosis in our in vitro hepatocyte steatosis and hypoxia model as evidenced by alterations in the expression of RIPK1, RIPK3 and MLKL." (PMID 33435617, 2021). "In support of this, we found that the expression of MLKL was upregulated in PHH cultured in steatosis-inducing conditions, but its expression returned to basal levels when these cells were treated with NSA, an MLKL inhibitor." (PMID 32094147, 2020).
glioma (16 papers, 2020 to 2025). A benign or malignant brain and spinal cord tumor that arises from glial cells (astrocytes, oligodendrocytes, ependymal cells). "Here, we show that elevated expression of key necroptotic machinery proteins, including RIPK1 and MLKL, is positively associated with disease progression and predicts poor prognosis in glioma patients." (PMID 41429922, 2025). "In conclusion, MLKL expression strongly associates with glioma patient overall survival, constituting a viable prognostic marker." (PMID 37651429, 2023). "A Cox proportional hazards model applied to 23 TCGA cancer cohorts identified RIPK1, RIPK3, and MLKL as significant risk factors for OS in WHO grade II and III gliomas." (PMID 41429922, 2025). "To investigate the role of RIPK1 and MLKL in glioma invasiveness, we performed Transwell migration and Matrigel invasion assays in U251 cells." (PMID 41429922, 2025). "Our data identify RIPK1 and MLKL as independent prognostic markers for glioma and reveal distinct roles for RIPK1 beyond its established function in necroptosis." (PMID 41429922, 2025). "Here, we integrate analyses of RIPK1, RIPK3, and MLKL across clinical glioma samples and experimental models to define the contribution of the necroptotic pathway to glioma pathobiology." (PMID 41429922, 2025). "In both TCGA and CGGA cohorts, tumors with wild-type IDH exhibited higher expression of RIPK1, RIPK3, and MLKL relative to IDH-mutant gliomas, consistent with the more aggressive clinical behavior associated with IDH-wild-type status." (PMID 41429922, 2025). "To investigate the role of RIPK1 and MLKL in glioma progression, we first examined their expression in relation to proliferative activity." (PMID 41429922, 2025). "Cytotoxicity against glioma cell line U251IC50 0.94 μMInduced necroptosis mainly by activating the RIP1/RIP3/MLKL pathway, exerted acceptable BBB permeability in mice, and inhibited U251 cell proliferation in an in vivo zebrafish xenograft model." (PMID 40362572, 2025). "In summary, this study identifies RIPK1 and MLKL as critical drivers of glioma progression and prognostic biomarkers." (PMID 41429922, 2025). "Collectively, these data highlight the association between necroptosis machinery and glioma aggressiveness, suggesting a pivotal role for RIPK1, RIPK3, and MLKL in disease progression and clinical outcome." (PMID 41429922, 2025). "In line with mRNA findings, RIPK1 and MLKL protein levels were higher in IDH-wild-type gliomas compared with IDH-mutant tumors." (PMID 41429922, 2025). "Together, these findings demonstrate that the necroptotic genes RIPK1, RIPK3, and MLKL are robust predictors of adverse clinical outcomes across glioma subtypes." (PMID 41429922, 2025). "To investigate the role of the necroptotic machinery in glioma, we analyzed the mRNA expression profiles of RIPK1, RIPK3, and MLKL across normal brain and glioma samples." (PMID 41429922, 2025). "Collectively, these results demonstrate that both RIPK1 and MLKL critically support glioma cell proliferation and tumorigenesis, with RIPK1 exerting a more potent role." (PMID 41429922, 2025). "To assess the prognostic significance of the necroptotic genes RIPK1, RIPK3, and MLKL in gliomas, we performed survival analyses across multiple datasets." (PMID 41429922, 2025). "In this study, we demonstrate that the necroptotic machinery genes RIPK1, RIPK3, and MLKL are highly expressed in gliomas and positively correlate with disease progression and patient prognosis." (PMID 41429922, 2025). "In a cohort of 81 clinical glioma samples, high Ki67 labeling indices (30–80%) were associated with significantly elevated RIPK1 and MLKL expression compared to low-Ki67 tumors (<30%)." (PMID 41429922, 2025). "In gliomas, a higher expression of MLKL is significantly correlated with poorer prognosis, confirming the view that MLKL and necroptosis play a tumor-promoting role in gliomas as opposed to other tumor types." (PMID 39062119, 2024).
glioma (continued). "Contrary to what was previously reported in other solid tumor patients, higher expression of MLKL was observed in patients with worst prognosis and reduced O.S., suggesting a detrimental role of necroptosis in glioma progression." (PMID 37651429, 2023). "In other words, considering two glioma patients with same age and molecular or histological diagnostics yet with distinct overall survival, the difference in MLKL expression level contributes to explain the observed discrepancy in this clinical outcome." (PMID 37651429, 2023). "Interestingly, higher expression of MLKL is associated with worse clinical outcome for adult-type diffuse glioma patients, which is opposite to what was found in other cell cancer types, suggesting that necroptosis undertakes an atypical detrimental role in glioma progression." (PMID 37651429, 2023). "In our studies, we found that the both the mRNA and protein levels of TNF-α, RIP1, RIP3 and MLKL were increased in glioma cells treated with emodin in vivo and in vitro for the first time." (PMID 30924024, 2020). "Treatment of U251 glioma cells with the RIPK1 kinase inhibitors Nec-1 or the MLKL oligomerization and membrane translocation inhibitor necrosulfonamide (NSA), respectively, had no significant impact on cellular growth, indicating that the pro-proliferative role of RIPK1 is kinase-independent." (PMID 41429922, 2025). "Since Ki67 is a well-validated marker of cellular proliferation, this finding suggests that RIPK1 and MLKL may contribute to the aggressive behavior of glioma." (PMID 41429922, 2025). "Given that MLKL is the executioner of the necroptotic pathway, we evaluated whether this gene would help to predict prognosis of adult gliomas patients." (PMID 37651429, 2023). "Interestingly, our data showed that necroptosis genes, except with the expression of MLKL, were significantly upregulated in glioma." (PMID 35719998, 2022). "Thus, our results suggested that osthole activated necroptosis via the RIP1/RIP3/MLKL signaling pathway in glioma U87 cells." (PMID 33350608, 2021). "Moreover, MLKL ablation may, at least in part, influence glioma cell-cycle progression through effects on RIPK1." (PMID 41429922, 2025). "RIPK1 was positively correlated with the expression of cyclin E1 (CCNE1), CDK2, TIMP1, N-cadherin (CHD2), and other genes implicated in glioma proliferation and invasion, whereas MLKL exhibited a weaker or negative correlation with most genes in this signature." (PMID 41429922, 2025). "Similar results were observed in the Chinese Glioma Genome Atlas (CGGA) dataset, where mRNA levels of RIPK1, RIPK3, and MLKL were elevated across glioma grades." (PMID 41429922, 2025). "Similar findings were observed in the CGGA dataset, where RIPK1, RIPK3, and MLKL served as independent prognostic indicators across all WHO grades and within grade III gliomas." (PMID 41429922, 2025). "Shikonin's antitumor effects on gliomas involve necroptosis mediated by RIP-1 or downregulation of CD147, with MLKL contributing through the promotion of chromatinolysis." (PMID 39619148, 2024). "To further explore the effect of Shikonin on necroptosis of glioma cells, we detected necroptosis-related proteins RIP1, RIP3, and MLKL expression levels of U251, U87, T98G cells treated with Shikonin (0, 4, 8, and 12 mM) for 24 hr." (PMID 39619148, 2024). "To validate these findings, we performed Western blot analyses across a clinical cohort of 81 glioma samples (16 grade II, 19 grade III, and 46 grade IV), which revealed significant upregulation of RIPK1 and MLKL and downregulation of RIPK3 in grade IV tumors relative to lower-grade gliomas." (PMID 41429922, 2025). "Glioma cells often manipulate the necroptosis pathway to avert cell death, including the inhibition of RIPK1/RIPK3 activity and the prevention of downstream mixed lineage kinase domain-like protein (MLKL) translocation." (PMID 39184045, 2024).
glioma (continued). "We observed an upregulation of programed necrosis-related proteins MLKL/RIPK3 and a concomitant downregulation of RIPK1 expression in glioma cell lines U251, U87, A172, and T98G, as well as in an in vivo subcutaneous tumor model, following Shikonin interventions." (PMID 39619148, 2024). "MLKL promotes shikonin-induced necroptosis in glioma cells by promoting chromatin lysis, and shikonin induces positive feedback between MLKL and its upstream signals RIP1 and RIP3, thereby promoting the death of glioma including GBM cells." (PMID 38304870, 2024). "The high expression of TLR3 in lower grade glioma (LGG) and LUSC; FASLG in LGG, UVM, KIRC, and THYM; RIPK3 in LGG, KIRC, and LUSC; RIPK1 in LGG and THCA; FAS in LGG, UVM, and THYM; MLKL in LGG, UVM, and LUAD; FADD in LGG and HNSC; and TNF in UVM and CESC was associated with poor survival." (PMID 35748782, 2022). "One study found that osthole is a potential drug for treating gliomas, as it increases the production of ROS and upregulates the expression of induced receptor interacting protein kinase 1 (RIP1), RIP2, and mixed lineage kinase domain-like protein (MLKL)." (PMID 35935861, 2022).